ENSG00000276643
Synonyms: LOC124901524
Gene: Small nucleolar RNA gene on chromosome 6 (166,099,853 to 166,099,924, forward strand). Ensembl gene ENSG00000276643.
Gene Ontology:
Biological process: RNA processing
Cellular component: nucleolus
Homologues: Orthologues: rat Snord45l1 (72% identical). Paralogues in human: SNORD45B (90% identical), SNORD45A (79% identical), SNORD45C (78% identical).